CASP9 (caspase 9)
Diseases named in the same sentence as CASP9 in open-access papers (continued):
Sharing a sentence is not in itself a finding about the gene and the disease.
Hepatitis (1 paper, 2015). Inflammation of the liver. "The increase in Bcl-2 and the reduction in Bax and caspase 9 indicate that astaxanthin inhibits the JNK/p-JNK pathway, and that the phosphorylation of Bcl-2 has an antiapoptotic effect in ConA-induced hepatitis." (PMID 25761053, 2015).
hippocampal atrophy (1 paper, 2020). "Numerous studies have revealed that hippocampal atrophy is mainly caused by neuronal loss, so we evaluated the protein level of NeuN, a specific neuron marker, and the level of cleaved-caspase-3 and cleaved-caspase-9, markers of apoptosis." (PMID 32267832, 2020).
Hyperinsulinemia (1 paper, 2020). An increased concentration of insulin in the blood. "Moreover, we have demonstrated reduced expression of CASP3 and CASP9, which are the crucial mediators of programmed cell apoptosis especially in the cells affected by hyperinsulinemia." (PMID 32880856, 2020).
hypoxia (1 paper, 2023). A decrease in the amount of oxygen in the body. "Recently, caspase-9 has been identified as a potent regulator of edema, gliosis, and neuronal dysfunction during acute retinal hypoxia." (PMID 37449272, 2023).
Immunodeficiency (1 paper, 2021). Failure of the immune system to protect the body adequately from infection, due to the absence or insufficiency of some component process or substance. "Human genetic evidence implicates caspase-9 loss of function mutations with neural tube defects, pediatric tumors, and immunodeficiency/lymphoproliferation." (PMID 34305609, 2021).
Insulin resistance (1 paper, 2025). Increased resistance towards insulin, that is, diminished effectiveness of insulin in reducing blood glucose levels. "Another important parameter when evaluating the damage caused by insulin resistance in the cell is the level of caspase-9, one of the inducers of caspase-3." (PMID 40729004, 2025).
insulinoma (1 paper, 2017). "In a rat insulinoma cell line such as the INS-1O, for example, overexpression of AT2R induces caspase-8, caspase-9, and caspase-3 cleavage and decreases Bcl-2, pAkt, and pERK expression levels." (PMID 28599664, 2017).
intrauterine growth restriction (1 paper, 2021). "In ovine placentas, CASP3 and CASP9 proteins increase toward term, and the levels of active CASP3 and CASP9 are increased in placentas with intrauterine growth restriction pregnancy compared with normal pregnancy." (PMID 33644157, 2021).
ischemic cardiomyopathy (1 paper, 2021). Ischemic cardiomyopathy is a cardiomyopathy in which a weakness in the muscle of the heart due to inadequate oxygen delivery to the myocardium with coronary artery disease being the most common cause. "In contrast, a recent study examined myocardial biopsies from patients with ischemic cardiomyopathy, and did not detect increased expression of either cl-caspase-9, cl-caspase-3, or cl-caspase-8 compared to aortic stenosis controls." (PMID 34305609, 2021).
kidney cancer (1 paper, 2024). Primary or metastatic malignant neoplasm involving the kidney. "Significant associations between the expression of “CASP9” (OR 0.66; 95% CI 0.54–0.79; P = 1.32 × 10−5) with kidney cancer were also mentioned." (PMID 38659038, 2024).
laryngeal carcinoma (1 paper, 2017). Carcinoma that arises from the laryngeal epithelium. "The anticancer saponin, dioscin induced apoptosis and cell cycle arrest in human laryngeal cancer by elevating the levels of p38, caspase 9 and Bax." (PMID 28223935, 2017).
lentivirus infection (1 paper, 2023). Virus diseases caused by the Lentivirus genus. "Moreover, caspase 3 activity, cleaved caspase 3 and cleaved caspase 9 levels were all elevated in HOKs after shGSDMC-lentivirus infection, noting that GSDMC knockdown induced cell apoptosis in HOKs." (PMID 37741915, 2023).
liver disease (1 paper, 2025). "This is consistent with studies reporting that curcumin reduces Casp-3 and Casp-9 levels in liver disease models." (PMID 40584441, 2025). "CXE is proven to suppress NO, pro-inflammatory (IL-6, IL-1β, and LDH), and apoptosis genes (Casp-9, Casp-3, and JNK) in APAP-mediated liver cells while increasing the expression of an anti-inflammatory agent (IL-10), which can be a potent target for liver disease treatment." (PMID 40584441, 2025).
malignant glioma (1 paper, 2015). A grade III or grade IV glioma arising from the central nervous system. "Importantly, shRNA mediated downregulation of BIM in the malignant glioma cell lines LN-229 and U87MG led to an attenuated cleavage of caspase-9 and, consequently, reduced the level of apoptosis following TMZ and ACNU treatment." (PMID 26418950, 2015).
malignant mesothelioma (1 paper, 2016). A malignant neoplasm of the pleura or peritoneum, arising from mesothelial cells. "Previously, we reported that Quercetin in combination with Cisplatin inhibits cell proliferation and activates caspase-9 and -3 enzymes in different malignant mesothelioma cell lines." (PMID 27514524, 2016).
memory-impaired (1 paper, 2025). "It significantly modulated the oxidative stress markers (SOD, GSH, CAT, MDA, and NO), inflammatory cytokines (IL-6, IL-1β, TNF-α), neurotrophic factors (CREB, BDNF), apoptotic markers (NFkB, caspase-3, caspase-9), and neurotransmitters (NE, DA, and GABA) in METH-induced memory-impaired rats." (PMID 41010958, 2025).
meningitis (1 paper, 2020). A disorder characterized by acute inflammation of the meninges of the brain and/or spinal cord. "Furthermore, upregulated levels of TSPO, cytochrome c, and caspase-3 and caspase-9 were observed in the rat hippocampus 10 days after meningitis induction with a simultaneous reduction in cardiolipin levels." (PMID 31901235, 2020). "Ten days after meningitis induction, the levels of both the cellular markers, caspase-3 and caspase-9, were increased (P < 0.05) in the hippocampus with no significant changes in the 24-h group except caspase-3 which was increased significantly (P < 0.05) in meningitis group hippocampus." (PMID 31901235, 2020). "Acute meningitis induction also elevated TSPO, cytochrome c, and caspase-3 levels with no change in caspase-9 levels." (PMID 31901235, 2020).
microcephaly (1 paper, 2013). A congenital or acquired developmental disorder in which the circumference of the head is smaller than normal for the person's age and sex. "Notably, NAC treatment strongly reduced cell death in morphants and counteracted the increased level of caspase-9 activation observed in the mitochondrial fractions from morphant embryos, as compared to that of controls, finally rescuing both microphthalmia and microcephaly." (PMID 23239471, 2013).
multiple system atrophy (1 paper, 2021). Multiple system atrophy (MSA) is a neurodegenerative disorder characterized by autonomic failure (cardiovascular and/or urinary), parkinsonism, cerebellar impairment and corticospinal signs with a median survival of 6-9 years. "Rodent and nonhuman primate models of multiple system atrophy offer experimental tools to investigate cell-specific consequences of caspase-9 activation in neurons and glia and enable studies to test the therapeutic potential of caspase-9 inhibitors as a neuroprotective strategy in MSA." (PMID 34305609, 2021).
muscular atrophy (1 paper, 2017). The loss of muscle tissue due to inactivity or disease. "We established, in real time, the kinetic of miRNA-23a expression during development of this disease and examined the potential implication of the miRNA 23a/APAF-1/Caspase 9 axis of regulation in the apoptosis of skeletal muscle undergoing muscular atrophy." (PMID 28493972, 2017).
Myocardial fibrosis (1 paper, 2021). "A study reported that miR-133a-3p inhibits cardiomyocyte apoptosis by targeting caspase-9, and miR-133a-3p has been implicated in the control of myocardial fibrosis." (PMID 34332589, 2021).
myocardial ischemia (1 paper, 2023). A disorder of cardiac function caused by insufficient blood flow to the muscle tissue of the heart. "The study showed the anti-apoptotic and cardioprotective effects of P. reptans extract against myocardial ischemia/reperfusion injury via inhibiting the expression of Caspase-9 and Caspase-3." (PMID 37525174, 2023).
nasal polyps (1 paper, 2023). "We theorize that the improvement in his sense of smell may have resulted from oxaliplatin-induced destruction of his nasal polyps through the caspase-9/procaspase-9 apoptotic pathway, a pathway shared with other mechanisms of nasal polyp destruction." (PMID 37674764, 2023).
neural tube defect (1 paper, 2021). A congenital defect characterized by failure of the neural tube to close completely; this results in the presence of openings in the brain or spinal cord. "A more recent sequencing study of Chinese cases with a neural tube defect (NTD) found more rare harmful variants in CASP9 compared to matched controls and documented lower expression of this gene in cell culture when exposed to low folate levels." (PMID 33937227, 2021).
Niemann-Pick disease, type C1 (1 paper, 2022). Type C Niemann-Pick disease associated with a mutation in the gene NPC1, encoding Niemann-Pick C1 protein. "Additional therapeutic strategies to target downstream apoptosis pathways include the use of either the caspase-9 inhibitor taurine or the caspase-3 inhibitor Z-DEVD-FMK, and these have been reported to show some therapeutic efficacy in a neuronal cell model of Niemann–Pick disease, type C1." (PMID 36142486, 2022).
ovarian failure (1 paper, 2025). "Consequently, activation of oxidative stress and ER stress by CIS explains high level of caspase 9 that was observed causing ovarian failure, necrosis and hemorrhage." (PMID 41028411, 2025).
pancreatitis (1 paper, 2017). Inflammation of the pancreas. "Thus, XIAP deletion promotes caspase-3 and caspase-9 activation, which mainly mediate the intrinsic apoptotic pathway, resulting in increased apoptosis during cerulein+LPS-induced pancreatitis." (PMID 28300832, 2017).
pelvic organ prolapse (1 paper, 2017). Abnormal descent of a pelvic organ resulting in the protrusion of the organ beyond its normal anatomical confines. "Similarly, Western blot analysis showed the expression of proapoptosis proteins (Bax and Bad), Cytochrome-c, cleaved caspase-3, and caspase-9 in patients with pelvic organ prolapse was upregulated." (PMID 29230415, 2017).
pemphigus (1 paper, 2023). Pemphigus is a group of rare autoimmune diseases that cause blistering of the skin and mucous membranes (mouth, nose, throat, eyes, and genitals).This conditioncan occur at any age, but often strikes people in middle or older age. "The binding of PV IgGs that antagonize mitochondrial nAChRs results in the opening of the mPTP; the release of CytC; caspase-9 activation; and the induction of apoptosis cascades, which represents a unique mechanism of keratinocyte damage in pemphigus termed apoptolysis." (PMID 36979046, 2023). "For example, whilst the pathophysiology of anti-Dsg pemphigus is dominated by the activation of p38MAPK and is associated with desmosome disassembly, anti-Dsc3 and anti-SPCA1 AuAbs activate SRC proto-oncogene, cytochrome c release, and caspase-9 activity in patients with anti-Dsg-negative PV." (PMID 36979046, 2023).
perinatal asphyxia (1 paper, 2020). A disorder caused by a lack of blood flow or gas exchange to or from the fetus in the period immediately before, during, or after the birth process. "In addition, DIM inhibited apoptosis and oxidative stress accompanying perinatal asphyxia through: downregulation of FAS, CASP-3, CAPN1, GPx3 and SOD-1, attenuation of caspase-9 activity, and upregulation of anti-apoptotic Bcl2 mRNA." (PMID 32816128, 2020).
periodontal disease (1 paper, 2021). "Additionally, elevated gingival crevicular fluid and serum concentrations of CASP3 and CASP9 have been observed in periodontal disease, i.e., gingival inflammation." (PMID 33435582, 2021).
pneumococcal pneumonia (1 paper, 2007). A febrile disease caused by STREPTOCOCCUS PNEUMONIAE. "Apoptosis localization in lung tissues during pneumococcal pneumonia was performed by in situ-TUNEL assay and by specific immunostaining of active caspase-9." (PMID 17257395, 2007).
pneumonia (1 paper, 2024). An acute, acute and chronic, or chronic inflammation focally or diffusely affecting the lung parenchyma, caused by an infection in one or both of the lungs (by bacteria, viruses, fungi, or mycoplasma.). "Interestingly, the present results showed that EGCG, through the modulation of BCL-2, BAX, CASP-3, and CASP-9, prevented pneumonia-induced apoptosis." (PMID 38580929, 2024). "The findings of the present study revealed that in the animal model of pneumonia, the level of BCL-2 was significantly reduced, while other apoptotic markers including BAX, CASP-3, and CASP-9 were remarkably increased." (PMID 38580929, 2024).
preeclampsia (1 paper, 2018). Preeclampsia is a hypertensive disorder of pregnancy that is characterized by new-onset hypertension with proteinuria presenting after 20 weeks of gestation, and depending on mild or severe forms may initially present with severe headache, visual disturbances, and hyperreflexia. "In placenta from term preeclampsia, we found a decrease in pro-apoptotic BAX and an increase in anti-apoptotic BCL2, as well as no change in CASP9, demonstrating active mitochondrial suppression of apoptotic signalling and suggesting that mitochondria promote cell survival in these placentae." (PMID 30455461, 2018).
primary effusion lymphoma (1 paper, 2023). A large B-cell lymphoma located in the body cavities, characterized by pleural, peritoneal, and pericardial fluid lymphomatous effusions and that is always associated with human herpes virus-8 (HHV-8). "Cells from primary effusion lymphoma (PEL), a non-Hodgkin’s B-cell lymphoma, were treated with arctigenin which markedly inhibited the proliferation of PEL by decreasing cellular ATP levels, disrupting mitochondrial membrane potential and triggering caspase-9-mediated apoptosis." (PMID 37189352, 2023).
primary hypertension (1 paper, 2018). "Moreover, cardiac cells of rats with primary hypertension were also characterized by downregulation of antiapoptotic protein B-cell lymphoma 2 (Bcl-2) and the release of cytochrome c from mitochondria resulted in caspase 9 activation." (PMID 30223427, 2018).
pulpitis (1 paper, 2021). Inflammation of the dental pulp. "Since CASP9 is involved in cell apoptosis in human dental pulp stem cells from deciduous teeth and also activation of caspase-9 can lead to activation of downstream caspase-8, CASP8 can be therefore assumed to be involved in the signaling pathway of apoptosis in the pathogenesis of pulpitis." (PMID 33777260, 2021).
renal fibrosis (1 paper, 2021). A final common manifestation of a wide variety of chronic kidney diseases characterized by glomerulosclerosis and tubulointerstitial fibrosis. "Last, the lesser inflammation was associated with lower renal fibrosis and expression of profibrotic genes (Col1a1, Col3a1, Fn1, and Vim) in UUO kidney of Casp9 HZ mice." (PMID 34739325, 2021). "At the same time, expression of inflammatory cytokines (Il1b, Csf2, Tnfa, and Cxcl10), renal fibrosis, and profibrotic genes (Col1a1, Col3a1, Fn1, and Vim) was lower in the FA-treated Casp9 HZ mice." (PMID 34739325, 2021). "Mice with genetic deletion or pharmacological inhibition of CASP9 showed lower apoptosis while having improved mitophagy, resulting in dampened activation of cytosolic nucleotide sensing pathways (cGAS-STING), reduction of inflammation, and protection from acute kidney disease or renal fibrosis." (PMID 34739325, 2021).
retinal degeneration (1 paper, 2022). Degeneration of the retina. "The relative mRNA expression of the apoptosis-related genes BAX, BCL2, CASP3, CASP8, and CASP9 was analyzed to study the events associated with the apoptosis process during spontaneous retinal degeneration." (PMID 35221932, 2022).
retinal disease (1 paper, 2021). "Studies reporting increased level of caspase-9 in retinal disease." (PMID 34305609, 2021).
salivary gland carcinoma (1 paper, 2026). A carcinoma that arises from the major or minor salivary glands. "On A253 human salivary gland carcinoma cells, GR extract elicited a dose-dependent antiproliferative effect, produced morphological changes, and increased ROS and both caspase-3/7 and caspase-9 levels." (PMID 41897443, 2026).
SARS-CoV infections (1 paper, 2022). "It was found that 45.87% of the associated genes (CASP3, CASP9, MAPK1, MAPK3, XIAP) contributed to cytochrome C-mediated apoptotic response and 3.67% of the associated genes (BECN1, FXYD2, GSK3B, HSP90AA1, ITGB1, MAP1LC3B) contributed to SARS-CoV infections." (PMID 36164436, 2022).
schwannoma (1 paper, 2018). A benign, usually encapsulated slow growing tumor composed of Schwann cells. "Similarly, curcumin treatment in RT4 schwannoma cells exerted cytotoxicity and activated caspase-3, caspase-9, and PARP, all of which are apoptotic proteins." (PMID 30534000, 2018). "In conclusion, curcumin was cytotoxic to RT4 schwannoma cells and enhanced the expression of apoptotic proteins such as PARP, caspase-3, and caspase-9, as well as the number of TUNEL-positive cells." (PMID 30534000, 2018).
spina bifida cystica (1 paper, 2020). A congenital abnormality in which the spinal cord and meninges protrude through a defect in the spinal column. "In the one case of thoracic spina bifida cystica there was a PDRV in apoptosis gene CASP9 (P = 0.042)." (PMID 32650820, 2020).
subarachnoid hemorrhage (1 paper, 2021). A serious neurological disorder characterized by intracranial hemorrhage into the subarachnoid space. "Previous results showed that the blockade of mGluR1, which belongs with mGluR5 to Group I mGlu subfamily, attenuates subarachnoid hemorrhage-induced cerebral vasospasm via enhancing eNOS and decreasing active caspase-9, and active caspase-3." (PMID 33668105, 2021).
synucleinopathy (1 paper, 2009). A neurodegenerative disease that is characterized by the abnormal accumulation of aggregates of alpha-synuclein protein in neurons, nerve fibers or glial cells. "Cleaved capase 9 immunoreactivity has been reported in viral vector-based models of synucleinopathy, so we evaluated activation of caspase 9 in end-stage hA30Pα-syn mice." (PMID 19680561, 2009).
temporal lobe epilepsy (1 paper, 2022). A localization-related (focal) form of epilepsy characterized by recurrent seizures that arise from foci within the temporal lobe, most commonly from its mesial aspect. "In temporal lobe epilepsy, the extrinsic apoptotic pathway predominates since caspase-8 activation precedes mitochondrial dysfunction and caspase-9 activation." (PMID 36293411, 2022).
teratoma (1 paper, 2022). A non-seminomatous germ cell tumor characterized by the presence of various tissues which correspond to the different germinal layers (endoderm, mesoderm, and ectoderm). "They used targeted integration to express an inducible caspase 9 activated by the BB homodimerizer at the end of the NANOG gene using a 2A sequence, showing the ability to prevent or ablate teratomas." (PMID 36189285, 2022).
thalassemia (1 paper, 2022). An inherited blood disorder characterized by a decreased synthesis of one of the polypeptide chains that form hemoglobin. "Increased cell death was distinctly present only in homozygous β0-thalassemia erythroblasts and associated with the up-regulation of pro-apoptotic (Caspase 9, BAD, and MTCH1) genes and down-regulation of the anti-apoptotic BCL-XL gene." (PMID 36143003, 2022). "Interestingly, significant down-regulation of anti-apoptotic BCL-XL gene but up-regulation of pro-apoptotic Caspase 9, BAD, and MITCH1 genes was observed on day 12 of homozygous β0-thalassemia cells compared to normal cells." (PMID 36143003, 2022).